EGFR (epidermal growth factor receptor)
Diseases named in the same sentence as EGFR in open-access papers (continued):
Sharing a sentence is not in itself a finding about the gene and the disease.
tumor (continued). "Tumor tissues are known to contain both tumor cells and normal cells, with transitional and apoptotic cells also included, the EGFR mutations in separate regions of the same tumor tissue may be highly heterogeneous." (PMID 31555581, 2019). "Therefore, the anti-tumor activity of PCC0208027 was associated with the simultaneous inhibition of EGFR and HER2 activation and blockade of RAF/MEK/ERK and AKT/mTOR signaling pathways." (PMID 30952931, 2019). "However, in the PD-L1 high expression group nivolumab showed a similar benefit to the TKI based regimens in patients with EGFR mutation positive tumor types." (PMID 30987609, 2019). "In addition, increased EGFR pathway activity is also necessary for Notch loss-induced ISC-like tumor growth." (PMID 30982741, 2019). "Moreover, 4 of 13 EGFR mutation-positive cases had additional follow-up tumor tissues due to further surgical resection or rebiopsy after initial diagnosis." (PMID 31221183, 2019). "The current study indicated that immune status in the tumor microenvironment may be important for the effectiveness of nivolumab in NSCLC patients with EGFR mutations." (PMID 30978241, 2019). "While we do not expect that following chemotherapy tumors might lose the expression of the EGFR mutation that is quite often a clonal event, the levels of cfDNA correlate with the tumor burden." (PMID 31557965, 2019). "The immune status of tumor microenvironment may predict antitumor effects of nivolumab in patients with EGFR mutations." (PMID 30978241, 2019). "TTS1 are effective later line chemotherapy, especially in tumor EGFR mutated patients." (PMID 31579626, 2019). "Since a significant number of patients acquire RAS-mediated resistance during EGFR-directed treatment, understanding the molecular mechanism underlying these antibody-mediated tumor-promoting effects is of relevance to design more resistance-preventive treatment approaches." (PMID 32039027, 2019). "EGFR mutation detection by tumor tissues, as well as cell blocks and exosomes in MPEs." (PMID 31608233, 2019). "Survival analyses revealed the association between mesothelin expression and poor overall survival, whereas lack of PTEN protein expression associated with lower progression-free survival with anti-EGFR-based therapy in the first-line setting for patients with RAS wild-type tumour." (PMID 31537838, 2019). "However, after satisfactory responses for a period, patients' tumours acquired resistance to first-generation TKIs because of the development of a T790M mutation, which affects the ATP-binding site of the human EGFR." (PMID 31598253, 2019). "However, the EGFR mutations spatial distribution characteristics remains poorly investigated, which is critical to tumor heterogeneity analysis and precision diagnosis." (PMID 31555581, 2019). "In addition, an increase in the detection rate has been shown to be proportional to tumor size and tumors with common EGFR-activating mutations." (PMID 31426797, 2019). "In this study, we found a similar association between tumor differentiation and EGFR CNAs." (PMID 31159251, 2019). "One hypothesis is that EGFR signaling is associated with cytotoxic chemotherapy induced tumor cell apoptosis." (PMID 31579626, 2019). "EGFRvIII is the most prevalent ligand-independent phenotype of EGFR alterations, and might causes a tumor-promoting chronic inflammation." (PMID 31801484, 2019). "Therefore, the identification of RAS mutations in tumor tissues to determine patients that are more likely to benefit from anti-EGFR therapies has become standard in the pretreatment management of patients with mCRC." (PMID 31253124, 2019). "The E19del and L858R mutation of EGFR can result in the sensitivity of tumor cells to EGFR-TKIs." (PMID 31344053, 2019).
tumor (continued). "For instance, mice lacking EGFR or several ligands for EGFR show retarded growth throughout the intestine, while dysregulated activation of EGFR caused by depletion of Lrig1, a negative regulator of EGFR, leads to intestinal stem cell expansion and tumor formation." (PMID 30974867, 2019). "Thus, our observations suggest that CXCR7 overexpression is one of the survival mechanisms in KRAS-dependent tumor cells with EGFR loss or cells treated with EGFR-TKIs." (PMID 30935067, 2019). "However, tumor patients tend to display deregulated EGFR activity, mostly due to point mutations, exon 8 deletion or gene amplification." (PMID 30956774, 2019). "Although we could analyze a limited number of patients for which tumor samples were available, we identified variants in several genes that might be potentially involved in the resistance to anti-EGFR agents." (PMID 31226844, 2019). "Thus, the use of liquid biopsy methods is a valuable alternative to tissue-based testing to identify patients eligible for anti-EGFR therapy in routine clinical practice, avoiding the sample bias associated with intra- and inter-tumor heterogeneity." (PMID 31222012, 2019). "Moreover, patients who were detected as EGFR mutation by exosomes but wild type by cell blocks or tumor tissues finally indicated as PR or SD." (PMID 31608233, 2019). "Among body fluid supernatant free DNA, body fluid sedimentary tumor cells, and plasma free DNA samples, the tumor EGFR gene mutation frequency of body fluid supernatant free DNA was significantly higher than that of body fluid sedimentary tumor cells and plasma free DNA specimens." (PMID 31602787, 2019). "Moreover, NSCLC patients with a high T790M/activating EGFR-mutation ratio in tumor samples or in plasma cfDNA have displayed a significantly better RR to second-line osimertinib and a longer PFS than patients with a low ratio." (PMID 31266248, 2019). "Uncontrolled EGFR-signaling is associated to hypoxia, while preclinical and clinical investigations have shown that EGFR-TKIs can increase the hematic flow through the tumor tissue and reduce hypoxia." (PMID 31266248, 2019). "Thus, future in vitro and in vivo studies are needed to fully elucidate the molecular mechanisms underlying the complex effects of anti-EGFR TKIs on the tumor–NK cell interaction." (PMID 31546690, 2019). "In December 2014, EGFR ex19del and T790M mutations were detectable in a new needle biopsy of the primary tumor; only at this time a digital PCR-based method was available for the analysis of circulating tumor DNA (ctDNA)." (PMID 31039766, 2019). "Also, some data indicate that these uncommon EGFR-mutants, although being often combined with each other in the same tumor, are rarely associated with mutations in other oncogenic drivers at baseline." (PMID 31266248, 2019). "Among body fluid supernatant free DNA, body fluid sedimentary tumor cells, and plasma free DNA samples, we found that the tumor EGFR gene mutation abundance of body fluid supernatant free DNA was significantly higher than that of body fluid sedimentary tumor cells and plasma free DNA specimens." (PMID 31602787, 2019). "These receptors are essential for the proliferation, differentiation, and apoptosis of tumor cells; thus, their inhibition by AFT prevents the growth and spread of tumor cells, including mutation-positive of epidermal growth factor receptor (EGFR−) NSCLC and metastatic head and neck cancers." (PMID 31611565, 2019). "For a more accurate EGFR mutations diagnosis, several research groups tried to apply laser capture micro-dissection to extract tumor materials in different tumor spatial regions and perform multiregional genomic sequencing to generate a comprehensive EGFR mutations spatial landscape." (PMID 31555581, 2019).
tumor (continued). "β-catenin levels were increased in NSCLC cells with oncogenic EGFR mutations, as well as in gefitinib-resistant cells, and inhibition of the Wnt/β-catenin pathway re-sensitised cells to EGFR inhibitors and increased their efficacy in these tumours." (PMID 30953094, 2019). "Using Real Time PCR, 26/42 (61.9%) cfDNA samples displayed the initial sensitizing EGFR mutation seen at the diagnosis in the primary tumor and 9/42 (21.4%) also showed a concurrent T790M mutation, whereas the remaining cases (16/42, 38.1%) resulted negative for both mutations." (PMID 31029076, 2019). "Here we explored the mechanisms and pharmacological interactions associated with the combination of inhibition of the most studied DNA repair protein MGMT and EGFR, a receptor tyrosine kinase to which is associated aggressive tumour progression and reduced drug sensitivity." (PMID 30416678, 2018). "In a multivariate Cox’s regression analysis, a low HIF-1α protein and a high EGFR protein level in the tumor were significantly associated with a better prognosis in STS patients compared to the groups II and III that showed similarly poor prognosis (RR = 3.1; p = 0.03 and RR = 3.4; p = 0.048)." (PMID 30513863, 2018). "In the smoking scenario, a tumor-initiating cell population acquires mutations at a high rate and hence accumulates a large number of passenger and relatively weak driver mutations, with low likelihood for early acquisition of dominant drivers like EGFR." (PMID 29335443, 2018). "Detecting EGFR mutations in serum or plasma has been proposed as an alternative to tumor tissue." (PMID 29930751, 2018). "In conclusion, we have revealed ERK activity dynamics regulated by two distinct upstream receptors, EGFR and ErbB2, in the intestinal epithelium and shown that alterations in the dynamics caused by Wnt signalling activation underlie the high sensitivity of tumour cells to EGFR inhibition." (PMID 29872037, 2018). "Therefore, we concluded that the discordant result is indeed due to underlying cellular heterogeneity in the tumor where different tumor clones are present, harboring different EGFR mutations." (PMID 29561830, 2018). "Whether the differences between these first-generation EGFR TKIs can cause different anti-tumor efficacy is controversial." (PMID 30068310, 2018). "One possible reason could be a low abundance of EGFR-mutated subclones that already existed in tumour tissue at the time of admission." (PMID 30029601, 2018). "A total of 106 consecutive patients with tumours bearing compound EGFR mutations were identified between January 2012 and May 2016; all patients received first-generation TKI therapy." (PMID 30055651, 2018). "The TCGA analysis suggested that no molecular driver mutations are significantly associated with a “T cell-inflamed” tumor microenvironment, though data on EGFR mutated samples suggested a marginally significant increase in “T cell-inflamed” tumors (7% in “non-inflamed” versus 17% in “inflamed”)." (PMID 29435109, 2018). "Moreover, we report for the first time that EGFR mutations are less frequent in patients with tumour size pT1a than in patients with tumour size pT1b and pT1c." (PMID 29849818, 2018). "To determine whether plasma was a good surrogate of EGFR mutation status in the tumour, we compared the EGFR mutation status in plasma samples (as determined by our assays) with the tumour status reported in hospital records." (PMID 29848757, 2018). "Fluorescent in situ hybridization (FISH) for MET-amplification, immunohistochemistry (IHC) for MET- and ALK-expression, and Next Generation Sequencing (NGS) for concomitant driver mutations were performed on EGFR-mutated tumor samples from erlotinib-treated patients." (PMID 29899852, 2018).
tumor (continued). "In addition, the patients, whose tumor sequencing showed the L858R mutation with AFs over 9%, were more sensitive to EGFR-TKIs than those whose AFs were below." (PMID 29566644, 2018). "ARMS (amplification refractory mutation system)-PCR was used to detect EGFR mutations in 107 (50 of pre-therapy, 29 after traditional chemotherapy and 28 after targeted therapy) cases of paired plasma and tumor tissue specimens, followed by comparing their concordance." (PMID 29764589, 2018). "Primary EGFR mutations derived from the analysis of corresponding tumor tissue of the analyzed 26 LB from 21 patient samples were composed of 15 point mutations (11 patients), 10 indels (9 patients) and one unknown status." (PMID 29719623, 2018). "Our retrospective observations suggested that the maximum tumor shrinkage rate with initial EGFR-TKI treatment might be one of the promising predictive biomarkers for emerging refractory tumors with the EGFR-T790M mutation." (PMID 30537950, 2018). "Enhancement of EGFR expression in a tumor is often associated with poor clinical outcome." (PMID 30510514, 2018). "Moreover, continuous exposure of tumor cells to TKIs transpires extra EGFR mutations and drug resistance, suggesting nuclear events of DNA sequence alteration and gene activation." (PMID 29855336, 2018). "Moreover, we reveal that Wnt signalling activation alters the ERK signalling dynamics, which underlies the enhanced responsiveness of tumour cells to EGFR inhibition." (PMID 29872037, 2018). "The mechanism underlying the association of carcinoembryonic antigen with EGFR mutations remains unclear, and molecular studies are needed to investigate the difference in proliferation and survival between tumours with exon 19 and exon 21 mutations." (PMID 29849818, 2018). "However, clinical detection of the EGFR-T790M mutation through tissue biopsy can be challenging due to risks associated with the biopsy procedure and because of spatial and temporal tumor heterogeneity." (PMID 29963252, 2018). "This study hints that EGFR activity is stimulated by tumor-associated bone cells." (PMID 30134822, 2018). "In addition, a higher proportion of patients with EGFR mutations had a tumor size of less than 30mm (60.4% vs. 43.6%, p < 0.001) and earlier stages (p < 0.001)." (PMID 29447182, 2018). "We believe the reduction in tumor size associated with early EGF treatment was due to EGFR-induced changes in the tumor microenvironment, including decreased cytokine expression, resulting in early epigenetic, mutational, or clonal reprogramming of tumor cells that retarded their overall growth." (PMID 29904166, 2018). "Though demonstrated here for EGFR targeting, the antigen versatility of the IgG-scTRAIL format facilitates the generation of tailor-made molecules to fight different cancer entities by addressing respective tumour-associated antigens on the cell surface." (PMID 29773864, 2018). "First-line therapy with an EGFR TKI (eg, erlotinib, gefitinib, afatinib) significantly prolongs progression-free survival (PFS) and is associated with significantly higher tumor response rate when compared with first-line cytotoxic chemotherapy for patients with EGFR mutations." (PMID 30148862, 2018). "The difference in the CCFs of these two driver mutations postulated that the EGFR mutation might drive tumor initiation, whereas the PIK3CA mutation contributed to tumor progression." (PMID 29738578, 2018). "The S-adenosylhomocysteine hydrolase inhibitor DZnep proved to efficiently target the enzyme and to impair tumor growth in a subset of NSCLC genotypes with epidermal growth factor receptor (EGFR) or BRG1 mutations when combined with the topoisomerase II inhibitor etoposide." (PMID 30487290, 2018).
tumor (continued). "Some image biomarkers may now be informative for predicting MGMT promoter methylation status or prognosis of glioblastoma, for prognosis for breast cancer, and for predicting EGFR mutation status or prognosis of non-small cell lung cancer." (PMID 30082856, 2018). "When the data were categorized by tumor histology type, EGFR mutations were detected in 20/108 (18.5%) tumor samples and 14/112 (12.5%) plasma samples from adenocarcinoma patients and in 2/34 (5.9%) and 3/40 (7.5%) samples from non-adenocarcinoma individuals, respectively." (PMID 29623586, 2018). "In addition, osimertinib also induced sustained tumor regression in an EGFR-mutated mouse brain metastases model." (PMID 29455654, 2018). "While dominant truncal drivers, such as EGFR mutations are an important prerequisite for efficacious targeted therapies, the evolutionary trajectory for each tumor can be augmented by additional genomic events in the natural life history, enhancing clonal fitness with emergent drug resistance." (PMID 29335443, 2018). "The ESMO Clinical Practice Guidelines for diagnosis and follow-up of metastatic NSCLC propose liquid biopsy as a surrogate source of tumor DNA and a new strategy for tumor genotyping, mainly at the time of progressive disease (PD) in patients with tumors having EGFR mutations." (PMID 29861862, 2018). "Mutated RAS may activate molecules downstream of EGFR, and consequently, inhibition of EGFR is largely ineffective in tumor entities with RAS mutations." (PMID 29463844, 2018). "Thus, the proportion of non-ADC patients in studied cohort will significantly affect the statistical result of the correlation between tumor size and EGFR mutation status." (PMID 29164298, 2018). "Increased activation of EGFR at the edges of tumor areas to induce EMT might be fulfilled by cancer-associated fibroblasts, myeloid-derived cells, or, as recently reported, endothelial cells secreting EGF and inducing EMT- and stem-like properties in HNSCCs." (PMID 30261040, 2018). "Significant association of EGFR expression was noted with tumor stage and disease-free survival." (PMID 29954411, 2018). "Tumor cells losing T790M mutation and maintaining EGFR activating mutation might benefit from first-generation EGFR-TKI treatment." (PMID 29713646, 2018). "Tumor cells losing T790M mutation and maintaining EGFR activating mutation might be benefit from first-generation EGFR-TKI treatment." (PMID 29713646, 2018). "Whilst this study has focused on characterizing the radiological phenotype associated with resistance to EGFR TKIs in xenografts, the same array of imaging biomarkers may inform on tumor response in patients with HNSCC." (PMID 30083516, 2018). "The aim of this pooled analysis is to combine and analyze simultaneously all the studies comparing ctDNA to tumor tissues based T790M-genotyping in order to provide a more precise estimation of the diagnostic accuracy of ctDNA analysis in patients with EGFR-mutant advanced NSCLC." (PMID 30190486, 2018). "While the subject of intense research, the complexity and plasticity of the tumor EGFR signaling network may underlie the poor response to current EGFR-targeted therapies." (PMID 30021161, 2018). "Also, directly sequencing cells extracted from tumor tissue has also been clinically accepted to detect EGFR mutation sequences." (PMID 30393665, 2018). "We assumed that EGFR mutations (exons 18, 19, 20, and 21) might decrease the expression of TF, which reduces tumor procoagulant activity and the incidence of VTE." (PMID 29743116, 2018). "The disadvantages could be that the discordance rate of EGFR mutations between the primary tumor and BMs can be as high as 32%, and the CSF penetration rate of gefitinib (1–10%) and erlotinib (2.5–13%) is limited." (PMID 29881714, 2018). "In addition to data on 1p/19q co-deletion, TERT promoter and IDH mutation, for 1955 of the tumours we had information on EGFR amplification and CDKN2A deletion status." (PMID 29460007, 2018).